PLCG1 (phospholipase C gamma 1)
Diseases named in the same sentence as PLCG1 in open-access papers (continued):
Sharing a sentence is not in itself a finding about the gene and the disease.
tumor (continued). "The pazopanib treatment resulted in a downregulation of p-PLCG1, p-AKT, and the expression of PI3K, indicating a potential inhibition of tumor cell growth and possible mechanisms via apoptosis." (PMID 38293667, 2023). "HLTF, ITGA10, PLCG1, and TTC3 are potential tumor antigens of STS for the development of mRNA vaccines." (PMID 35053609, 2022). "Based on the hazard ratio (HR), the downregulated PLCG1, CASP6, CASP4, and AIM2 were considered tumor suppressors, whereas the upregulated PRKACA, NLRP9, and BAK1 were regarded as oncogenes." (PMID 34805183, 2021). "IL6R, PLCG1, PTPN1, and HCK are involved in cytokine/interferon signaling to activate immune cells to counter proliferating tumor cells." (PMID 30978274, 2019). "When PLCγ1 conditional knockout mice were subjected to three cycles of DSS, we observed a 50% decrease in the incidence of tumors, and the average tumor load was lower than that in WT mice." (PMID 29464031, 2018). "In a CAC model, we showed that the deletion of PLCγ1 in IEC decreased the incidence of tumors by enhancing apoptosis and inhibiting proliferation during tumor development." (PMID 29464031, 2018). "The in vivo data obtained in the CLL-xenograft mouse model demonstrated that, by inducing PLCγ1-mediated, caspase-independent PCD, the injection of CD47 agonist peptides significantly reduced tumor burden." (PMID 25734483, 2015). "Another three IL4 pathway genes (PRKCZ, PLCG1, PIK3CD) that were down-regulated with tumor progression showed further decreased expressions after chemotherapy in the current study." (PMID 23451142, 2013). "ICAM1, PLCG1, PLCG2 and other genes in the pathway are also related to tumor migration." (PMID 37312215, 2023). "Finally, four potential tumor antigens were identified, each related to prognosis and antigen-presenting cell infiltration in STS: HLTF, ITGA10, PLCG1, and TTC3." (PMID 35053609, 2022). "Tumor-bearing nude mice treated with neoantigen (ACAD8-T105I, BCAR1-G23V and PLCG1-M425L)-induced NRTs exhibited significantly delayed tumor growth, whereas the irrelevant peptide-induced NRTs did not restrict tumor growth." (PMID 33928024, 2021). "The decrease in tumor incidence could explain the increase in apoptosis by the upregulation of Bak and cleaved PARP, and the downregulation of phospho-AKT, in tumors from PLCγ1 conditional knockout mice." (PMID 29464031, 2018). "RALA and PLCγ1 are new targets of miR-331-3p in PCa as determined by bioinformatics, microarray detection, and investigating of a non-malignant vs tumor cohort study." (PMID 28903407, 2017). "We also observed in this mouse model that PKHB1 reduced tumor burden by inducing PLCγ1-mediated PCD and that PKHB1 did not induce apparent toxicity in the tumor-engrafted mice." (PMID 25734483, 2015). "Our other study’s results showed that the depletion of PLCγ1 by shRNA could suppress tumor growth and metastasis in mice tumor xenograft model derived from BGC-823 cells with the transfection of sh-PLCγ1 vector (under review)." (PMID 26633375, 2015). "Of notice, study patients demonstrating high tumor PI3K-mediated signaling activity, as all array substrates of this specific pathway (PIK3R1, CTTN1, PLCG1, PDPK1, and RASA1) were highly phosphorylated, had particularly poor metastasis-free survival after radical treatment of the pelvic cavity." (PMID 23226389, 2012). "The results of this research showed that PLCγ1 silencing in IDH-wildtype LGG cell lines dramatically affects their progression, migration, and invasiveness and that the PLC-targeted drug significantly suppresses the tumor growth of both IDH-wildtype in vitro and mouse models." (PMID 37238668, 2023). "According to the Kaplan-Meier analysis, high expression of PLCγ1 or its activated forms was significantly correlated with lower DFS rates in patients with Luminal-A tumours, but not in patients with Luminal-B tumours, or HER2 positive or Triple Negative tumours." (PMID 31362705, 2019).
tumor (continued). "Thus, the GOBPs enriched in the PLCG1-low and -high RCC subgroups — metabolism and immune activation, and proliferation and morphogenesis, respectively — could all be related directly or indirectly to tumor vascular features." (PMID 37651195, 2023). "Besides, ALT impairs the angiogenesis and tumor growth by down-regulating vascular endothelial growth factor receptor 2 (VEGFR2) phosphorylation level and its downstream protein kinases, including phospholipase C gamma 1 (PLCγ1), protein tyrosine kinase 2 (FAK), SRC, and AKT." (PMID 34899346, 2021). "All signaling pathway inhibitors have pronounced negative effects on the viability of both GBM tumor cell lines but U87MGvIII is significantly more sensitive to the inhibition of casein kinase than the wild-type whereas the wild-type is more sensitive to the inhibition of PLCG1, ABL1 and BCL2." (PMID 31386654, 2019). "Several proteins in the PI3K/AKT pathway were found to be upregulated in activin (+) AOIs in the tumoral compartment, including PLCG1, Phospho-PRAS40, and Phospho-Tuberin, suggesting a possible switch to non-canonical PI3K/AKT signaling in tumor cells." (PMID 37296966, 2023).
cancer (83 papers, 2010 to 2025). A tumor composed of atypical neoplastic, often pleomorphic cells that invade other tissues. "Unsurprisingly, dysregulation of PLCγ1 or PLCγ2 activity is associated with multiple maladies including immune disorders, cancers, and neurodegenerative diseases." (PMID 38551930, 2024). "Recent bioinformatics analysis identified that PLCG1 was frequently highly expressed and mutated in various cancers and was involved in tumorigenesis as an oncogene." (PMID 36920176, 2023). "Both PLCγ isoforms are mutated in many cancers, and PLCγ1 positively drives tumorigenesis in the lung." (PMID 37370855, 2023). "We also observed an additional PLCG1 alteration, G797E, a known gain-of-function mutation in human cancers." (PMID 32210430, 2020). "In two cases, we found PLCG1 mutations, S273F and G797E, both corresponding to well-characterized oncogenic activating mutations in human cancers." (PMID 32210430, 2020). "For example, PIK3CA H1047R and PLCG1 S273F are frequently identified as activating mutations in human cancers." (PMID 32210430, 2020). "Several studies have implicated PLCγ1 as a regulator of cancer cell invasion and metastasis via multiple mechanisms." (PMID 29464031, 2018). "We also characterize the effect of the PLCγ1 Arg687Trp mutation—homologous to the cancer therapy resistance Arg665Trp substitution in PLCγ2—on the characteristics of the tandem SH2 domain." (PMID 29972810, 2018). "In CAC, the initial evidence for the functional relevance of PLCγ1 signaling was provided in a preclinical trial that demonstrated that many of these targets are associated with cancer initiation and progression." (PMID 29464031, 2018). "Meanwhile, we rescued the effect of shRNA/PLCγ1 on LC3B-II expression by transfecting the two types of cancer cells with pRK5, encoding an HA-tagged PLCγ1 (pRK5-PLCγ1) vector, to overexpress PLCγ1." (PMID 29066806, 2017). "PLC-γ1, the protein encoded by Plcg1, has been shown to upregulate cell migration and invasion in vitro and in vivo, including upregulating metastasis in cancer." (PMID 28513565, 2017). "Furthermore, in tandem SH2 and γSA constructs, molecular dynamics and NMR results show that the Arg687Trp mutant in PLCγ1 (equivalent to the cancer mutation Arg665Trp in PLCγ2) perturbs the dynamic allosteric pathway." (PMID 29972810, 2018). "Besides c‐Myc, overexpression of cylin D1 116 and phospholipase Cγ1 (PLCγ1) 117 has been linked with higher rates of cellular proliferation in many cancers." (PMID 26648178, 2016). "Activation of PLCγ1 is associated with increased invasion of cancer cells." (PMID 23185569, 2012). "Although PLCG1 promotes metastasis in several cancers, this is the first study showing that PLCG1 promoted PDAC metastasis." (PMID 39820281, 2025). "The level of expression and phosphorylation of phospholipase C-gamma 1 (PLCG1), which is involved in cell migration and metastasis of cancer cells, significantly decreased." (PMID 36982207, 2023). "In contrast, some studies have indicated that reduced PLCγ1 expression is conducive to cancer cell survival and proliferation." (PMID 37371495, 2023). "Another study highlighted a mechanism of cancer cell adaptation to hypoxia with potential therapeutic value for PLCγ1." (PMID 37370855, 2023). "Activation of this enzyme is associated with cancer cell migration and metastasis, which has resulted in PLCγ1 emerging as a potential therapeutic target for cancer treatment." (PMID 35574218, 2022). "PLCG1 has been reported to be a multifunctional protein abundant in most malignant tumors, including liver, lung, and prostate cancer." (PMID 34697421, 2022). "CHMP4C and CASP5 were hypomethylated in most cancer types, while PLCG1 and NLRP6 were hypermethylated in most cancer types." (PMID 35795676, 2022). "An exciting fact is that PLCγ1 can also inhibit cancer cell proliferation by binding with JAK2 and PTP-1B." (PMID 34793541, 2021).
cancer (continued). "Using phospho-peptide affinity chromatography and mass spectrometry, we found that PLCγ1 binds β4 at the phosphorylated residues Y1422/Y1440, but were unable to verify this interaction in A431 carcinoma cells that overexpress the EGFR." (PMID 33883672, 2021). "PLCγ1 is also known to be involved and to play an important role in cell invasion, metastasis and progression in cancers." (PMID 31548507, 2019). "2-O-Bn-InsP5 is able to inhibit the epidermal growth factor-induced PLCγ1 phosphorylation and activity, ultimately resulting in impaired cancer cell migration and invasion." (PMID 27199173, 2016). "Our previous study demonstrated that the PDK1/PLCγ1 complex is required for cancer cell migration and invasion." (PMID 27199173, 2016). "More importantly, we show that the 2-O-Bn-InsP5-mediated inhibition of PDK1/PLCγ1 complex assembly results in inhibition of cancer cell migration, invasion and in vivo dissemination using zebrafish xenotransplants." (PMID 27199173, 2016). "Others had already shown, as evidence of an involvement of PLCγ1 in cell motility, that a dominant negative fragment of PLCγ1 can impair the migration and invasiveness of cancer cells in vivo." (PMID 26295810, 2015). "Apart from its role in angiogenenesis, PLCγ1 is also required for cell migration and cytoskeleton remodelling in both cancer and normal endothelial cells." (PMID 26295810, 2015). "As a member of the PLC family, PLCγ1 is upregulated in several cancer cell lines and cancer tissues." (PMID 26096802, 2015). "Ardent investigation and flux of newly published papers suggest that miR-200 families impact cancer invasiveness by collaborating with other molecules, such as Notch, Twist1 and PLCγ1." (PMID 23372687, 2013). "Therapeutics that selectively activate PLCγ1 and PLCγ2 could be useful in certain cancer and neurodegenerative indications as well." (PMID 38551930, 2024). "Within this study, the drug-sensitivity analysis uncovered a negative correlation between the expression levels of the prognostic-related genes (PRGs) utilized in the model (IL18, CASP3, GSDMA, and PLCG1) and the majority of drugs present in the cancer therapeutic response portal database." (PMID 37561524, 2023). "Furthermore, the enzyme PLCγ1, a protein involved in cell growth and proliferation, has been known to play a role in cancer progression, yet the role of PLCγ1 in BCR-FGFR1-mediated malignancies is undetermined." (PMID 35574218, 2022). "We observed that NLRP7 (n = 8), AIM2 (n = 10), CASP8 (n = 6), GSDMA (n = 5), GSDMB (n = 8), and GSDMC (n = 12) mainly showed hypomethylation in most cancers, and PLCG1 (n = 11), NLRP6 (n = 13), ELANE (n = 11), CASP6 (n = 5), NLRC4 (n = 12), and PYCARD (n = 8) showed hypermethylation in most cancers." (PMID 35246158, 2022). "Epidermal growth factor receptor (EGFR) activates PLCγ1 and helps in cancer cell mitogenesis." (PMID 34793541, 2021). "Involvement of PLCγ1 in a number of cellular processes makes it an important drug target for a number of pathological and disease conditions, including immunological disorders and cancers." (PMID 31548507, 2019). "Indeed, PLCγ1 is known to play important normal physiological roles, such as cell survival; and proliferation, as well as roles in cancer metastasis, such as angiogenesis and vascular permeability." (PMID 29464031, 2018). "Phospholipase C, gamma 1 (PLCG1) is most notably characterized in cancer by activation of cellular proliferation in response to growth factors such as epidermal growth factor receptor (EGFR) and platelet derived growth factor receptor (PDGFR), both common pathways altered in GBM." (PMID 29946469, 2018).
cancer (continued). "Moreover, to date, the regulatory role of PLCγ1 with regard to autophagy in the two types of cancer cells is unclear." (PMID 29066806, 2017). "To determine whether PLCγ1 is involved in cancer cell migration, we assessed the effects of PLCγ1 shRNA2/3 in ruffling, transwell, and scratch assays." (PMID 26811493, 2016). "Furthermore, in cancer patients, PLCγ1 overexpression and increased phosphorylation levels are correlated with poor prognosis and metastasis formation." (PMID 26295810, 2015). "Consequently, PLCγ1 can be considered as a keyregulator in cell migration upon RTK signaling andthe development of new anti-cancer drugs could be anongoing research field around this protein." (PMID 31606964, 2020). "Interestingly, many of the DMGs identified had multiple roles and several were potential cancer biomarkers or were previously shown to be implicated in various types of cancers, including ABLIM1, ADAM12, ARHGEF4, FBLN2, ITGA6, LRPAP1, Ly9, NT5E, PITPNC1, PLCG1, OBSCN, RHOH, SPTBN1, SPOCK2 and SPRY1." (PMID 41159936, 2025). "As an effective pharmacological compound for cancer, LA induces apoptosis in different cancers via multiple pathways, including P13-Akt-mTOR, VEGFR2, c-Met, PLCγ1, MAPT, JNK/p38, and ERK1/2, along with a combination of regulatory targets." (PMID 35677438, 2022). "In fact, PDK1 regulated the EGF-induced PLCγ1 activation of MDA-MB-231 cells in a different AKT-independent manner, and the interaction of PDK1–PLCγ1 was proved to be important for cancer cell invasion." (PMID 35159078, 2022). "Compared with the human normal glial cell line (HEB), PLCG1, IL18, and IL6 were highly expressed in cancer cell lines (U251 and U87)." (PMID 36605437, 2022). "Among these signatures (TNF, TIRAP, CASP9, PLCG1, PRKACA, CASP3, CASP8, CASP4), TNF (Tumor necrosis factor) is currently considered a two-edged sword in cancer development." (PMID 35741587, 2022). "In particular, diet-modulated miRNAs were able to target and interfere with several genes mainly involved in cancer signal transduction pathways (e.g., EGFR, RAC1, PLCG1, FOS, NRAS, SOS2, etc.)." (PMID 32911851, 2020). "In the cell cycle pathway, GSK3B, CDK2, and CDK1 are reduced by cisplatin in each cell line, and in cancer pathways, cisplatin reduces phosphorylation of GSK3B, AKT1, PDGFRa/b, PLCG1/2, and CDK2." (PMID 31929796, 2019). "Hence, we considered the possibility that autophagy regulation by PLCγ1 may occur in cancer cells." (PMID 29066806, 2017). "Apart from its anti‐proliferative effects determined by MTT assay, platycodin D has been shown to inhibit the expressions of c‐Myc in U937 leukaemia cells 102, phosphorylated PLCγ1 in HUVECs 118 and cyclin D1 in PC3 prostate 45 and AGS gastric 73 cancer cells." (PMID 26648178, 2016). "PLCγ-1, a very important member of phospholipase-C (PLC) families, is up-regulated in many cancer tissues and cancer cell lines and has been found to participate in many physical processes." (PMID 23905676, 2013). "For instance, PLCγ1 expression is downregulated during hypoxia in KRAS-mutant human lung adenocarcinoma cell lines, preventing lipid peroxidation, inhibiting apoptosis, and enhancing cancer cell proliferation." (PMID 37371495, 2023). "Likewise, phospholipase C gamma 1 (PLCG1) and caspase 5/8 (CASP5/8) also exert antitumor effects in cancer." (PMID 35923703, 2022). "PLCG1 is a member of phospholipase C (PLC) family, which may be changed by kinase activity in the cancer progression." (PMID 36430822, 2022). "The link between PLCγ1 activity and the IL-6/STAT3 signaling pathway could account for the transcription of many important cancer-related genes." (PMID 29464031, 2018). "Overexpression of PLCG1 was correlated with five essential cancer-related processes and pathways: protein secretion, MYC targets, mitotic spindle, G2/M checkpoint, and E2F targets, which demonstrates that PLCG1 is possibly involved in the facilitation of cancer proliferation and adaptation." (PMID 34697421, 2022).
cancer (continued). "Our data show that when PLCγ1 is lacking in IECs, cancer incidence is reduced." (PMID 29464031, 2018). "Both within the CLL field and in the broader scope of cancer research, our mechanistic results regarding caspase-independent PCD and PLCγ1 pave the way for the development of novel pharmacological tools that could circumvent the chemotherapy resistance characterizing CLL cells." (PMID 25734483, 2015). "Potential off‐target sites that are not gRNA‐based but related to cancer genes were Metazoa‐SRP, RARA, and ACSL6 found in HLA‐A11R hESCs, and PLCG1 found in iC9‐HLA‐A11R hESCs." (PMID 37199039, 2023). "The other two significant proteins, PLCG1 and EZR (ezrin), were demonstrated to play critical roles in the metastatic potential of cancer cells but not in primary tumor growth." (PMID 21211025, 2011).